LGALS3 (galectin 3)
Diseases named in the same sentence as LGALS3 in open-access papers (continued):
Sharing a sentence is not in itself a finding about the gene and the disease.
tumor (continued). "In addition to galectin-3 and LSECtin, fibrinogen-like protein 1 (FGL1) is another important ligand for LAG-3 as a soluble protein that is released by the liver under normal conditions, and FGL1 is highly expressed in a few tumor tissues." (PMID 37055849, 2023). "However, the molecular regulatory mechanisms responsible for the level of expression of the Galectin-3 in tumor cells are not yet clear." (PMID 36936148, 2023). "Galectin-3 was expressed on multiple cell types, depending on the zone: leukocytes in the proximal zone, CSCs and fibroblasts in the border zone, and non-proliferating tumor cells in the distal and remote regions, respectively." (PMID 36672243, 2023). "The high levels of microsatellite instability, deficiency in mismatch repair, high density of tumor-infiltrating lymphocytes, high PD-L1 expression on tumor and immune cells, absence of Galectin-3 and distinct composition of the gut microbiota were associated with response to treatment." (PMID 35625643, 2022). "Both galectin-3 and B4GALT1 may affect signaling pathways involved in cell–cell communication, in tumor cell dissociation and invasion, in cell-matrix interactions, in tumor angiogenesis, in immune modulation, and in metastasis formation." (PMID 36499368, 2022). "Besides, galectin-3 might interact with ECM and form a tumor capsule, a fibrotic capsule that harasses migratory cells." (PMID 36713574, 2022). "Also in our study, a number of suppressive factors were identified that could be produced by UM cells (e.g., IL-6, galectin 3) and that may explain why we obtained the highest TIL expansion by separating T cells from their tumor environment." (PMID 36249685, 2022). "We describe changes in biological pathways across the normal to tumor spectrum and show that fibroblast growth factor (FGF) ligands are overexpressed in NPC tumors, while negative regulators of FGF signaling, including SPRY1, SPRY2, and LGALS3, are down-regulated early in carcinogenesis." (PMID 35394843, 2022). "However, the presence of γδ T cells is not sufficient to exert potent anti-tumor responses, because it has been shown that Galectin-3 which is expressed on PDAC cells but also αβ- and γδ T cells, inhibits T cell proliferation and is thus regarded as an intrinsic tumor escape mechanism." (PMID 34638420, 2021). "Binding of galectin-3 to TF on MUC1 of tumour cells induces MUC1 cell surface polarization and exposure of smaller cell surface adhesion molecules/ligands, leading to increase of tumour cell-endothelium adhesion and tumour cell–cell homotypic aggregation, two important steps in metastasis." (PMID 34223877, 2021). "This is not the only explanation of the role of galectin 3 in tumor metastasis." (PMID 32859099, 2020). "The expressions of Galectin-3 and Galectin-9 in tumor tissue and adjacent non-tumor tissue." (PMID 32995093, 2020). "Considerations about the potential of RGI in biological tumor control applications are centered on low molecular weight oligos obtained from RGI galactan side chains, because there is evidence supporting its participation on cellular signaling being good candidates for binding to Galectin 3 (Gal3)." (PMID 31067636, 2019). "Interestingly, in the absence of Gal-3 in the tumor microenvironment (Lgals3−/−), there was a reduction in the mRNA levels of CHST11 in 4T1-shRNA-Gal-3-derived tumors in comparison with 4T1-scramble-derived tumors." (PMID 31949431, 2019). "Though, LLC tumor cells also produce gal-3 (data not shown) and therefore the in vivo effects observed in Lgals3−/− mice may be rescued by this source." (PMID 28533486, 2017). "Moreover, galectin-3 levels are increased in invasive tumours compared with non-muscle invasive lesions." (PMID 29207682, 2017). "Our data demonstrated that the absence of host galectin-3 drastically affected the tumor biology." (PMID 27526676, 2016).
tumor (continued). "We then performed histological analysis of the primary tumor 21 and 28 days p.o.i. and found an increased necrotic area (p < 0, 01) and percentage of proliferative cells (p < 0, 05) in 4T1 tumors grown in the absence of galectin-3 (Lgals3−/−)." (PMID 27526676, 2016). "Here, we will discuss the involvement of galectin-3 in stress signaling pathways (MAPK family, from mitogen-activated protein kinase) and in the orchestration of both cell and tissue responses in stress conditions commonly found within the tumor microenvironment." (PMID 27242966, 2016). "While these studies have focused solely on the role of galectin-3, it is possible that truncated glycan structures may also disrupt the dense barrier surrounding tumor cells independent of galectin-3." (PMID 27483328, 2016). "We found that extracellular galectin-3 could increase the ability of H1299 to form tumor spheres (data not shown)." (PMID 25669973, 2015). "Galectin-3 has also been found to act as a chemo-attractant to endothelial cells and to stimulate neovascularization through vascular endothelial growth factor (VEGF) in the tumor stroma, thus contributing to the establishment of an escape route for metastatic cells." (PMID 26222311, 2015). "A subsequent study indicated that cleaved galectin-3 is more efficient than intact galectin-3 in exerting chemotactic forces upon endothelial cells through upregulation of phosphorylated FAK, possibly leading to enhanced tumoral angiogenesis, due to recruitment of these cells to the tumor site." (PMID 24982845, 2014). "But we showed higher cyclin D1 expression in galectin-3 negative tumor tissues." (PMID 22024187, 2011). "Here we showed a significant reduction in the proportion of galectin-3-expressing infiltrating macrophages/dendritic cells within the tumour microenvironment of WEB2170-treated mice but not in the spleen white pulp of animals treated with both DTIC and/or WEB2170." (PMID 20465821, 2010). "Thus, the interaction between circulating galectin-3 and TF-expressing MUC1 on the surface of disseminating cancer cells promotes cell aggregation and embolus formation and enhances survival of disseminating tumour cells in the circulation." (PMID 20565834, 2010). "C4.4A and galectin-3 expression also did not significantly vary depending on tumour grading." (PMID 17912244, 2007). "Furthermore, Galectin-3 expressed by a variety of cells in the tumor microenvironment instead of the tumor itself may interact with LAG3 on tumor-specific CD8+ T cells, thus resulting in the modulation of anti-tumor immune responses." (PMID 35958563, 2022). "Additionally, three novel LAG-3 ligands have been reported: galectin-3, liver sinusoidal endothelial cell lectin (LSECtin), and fibrinogen-like protein 1 (FGL1) which are abundantly present in the tumor environment to help regulate and effectively abolish anti-tumor immunity of CD8+ T cells." (PMID 31569553, 2019). "Additionally, due to the large differences in expression between the tumor groups, SST5 represents a potential new immunohistochemistry panel marker for PC in addition to the established markers parafibromin and Ki-67 and suggested markers galectin 3 and PGP9.5." (PMID 31336364, 2019). "Taken together, our results demonstrate for the first time that the absence of galectin-3 in the host microenvironment favors the growth of the primary tumors, the metastatic spread to the inguinal lymph nodes and bone marrow colonization by metastatic 4T1 tumor cells." (PMID 27526676, 2016). "Therefore, these in vitro data might explain the diminished angiogenesis observed in vivo when galectin-3 is absent in tumor cells and/or in the tumor stroma." (PMID 24982845, 2014). "LGALS3 overexpression is a consistent feature in both primary and metastatic PDAC, supporting its role in maintaining tumor aggressiveness rather than driving metastasis." (PMID 41153387, 2025).
tumor (continued). "Conversely, tumor cells exhibited positive staining for the three primary LAG-3 ligands (HLA-DR, FGL-1, and galectin-3), while being negative for PD-L1." (PMID 38336861, 2024). "Here, we have found that the LGALS3 upregulation occurred in parallel to the downregulation of C1GALT1 both in vitro and in vivo in tumor tissue, with a significant negative correlation between them." (PMID 36745330, 2023). "Both LGALS3 and LGALS3BP appear to have higher expression in mesenchymal cancer cells, regardless of the tumor immune phenotype." (PMID 38086828, 2023). "A breakdown of all the ligands targeting the LAG3 receptor on CD8+ T cells, regardless of cancer cell EMT status or tumor immune phenotype, showed that most ligands for LAG3 are HLA II molecules, with LGALS3 being the only non-MHC related ligand." (PMID 38086828, 2023). "Additional IHC (Lu-5, Galectin 3, PSA) was negative for tumor cells and showed unspecific reaction with staining of normal structures: macrophages, plasma cells and some tissue background." (PMID 30400793, 2018). "Thirdly, due to the insufficient studies, correlation between galectin-3 and OS or DFS/RFS/PFS in other tumor types has not been further analyzed." (PMID 30410421, 2018). "Other parameters, such as the expression level of galectin-3, Eastern Cooperative Oncology Group (ECOG) performance, gender, surgical method, age ≥ 50 years, tumor size, or radiation field were not significant factors." (PMID 29378529, 2018). "Here, we show that co-expansion of CD4+CD25hiFoxP3+ T cells and/or tumor cell produced IDO and galectin-3 during MLTC have a negative impact on the activation and expansion of tumor-specific T cells, and we describe different manners to circumvent this." (PMID 28401257, 2017). "Although extracellular galectin-3 per se has no influence in cellular apoptosis, it's binding to cell surface receptors such as EGFR can sensitize tumor cells to chemotherapeutics." (PMID 27835877, 2016). "In one reported case the tumor was thyroglobulin positive, but the authors did not test TTF-1 or galectin-3." (PMID 23819507, 2013). "Serum and plasma levels of Galectin-3 were similar between the two HGSC cohorts and healthy donors, suggesting that the increased levels of Galectin-3 are not systemic but localized to the tumor microenvironment." (PMID 39759523, 2024). "Tumor cells were positive for PTH and APC but negative for galectin-3 and PGP9.5." (PMID 38363524, 2024). "This is consistent with previous findings that optimal galectin-3 induction requires TCR signaling, and in the tumor microenvironment, galectin-3 is differentially expressed on the surface of tumor-antigen activated CD8+ T cells, but is absent in resting T cells." (PMID 33979626, 2021). "Finally, double positive tumor cells (CK-19+ and PCNA+) were present in greater numbers in the bone marrow of Lgals3−/− mice, regardless of the expression of Gal-3 in 4T1 cells." (PMID 31949431, 2019). "In tumour cells that evade the NK cells, galectin-3 binds to poly-N-acetyllactosamine in the NKG2D-binding site of MICA, thereby preventing the interaction of MICA with NK2GD, and the apoptotic mechanisms are not triggered to promote longer circulation of the tumour cells." (PMID 37444377, 2023). "Furthermore, tumor microenvironment galectin-3 was shown to interfere with TAM recruitment, because infiltrating CD68+ cells were observed into the tumor mass, while these cells were only found in the periphery of galectin-3 negative tumors engrafted in KO mice." (PMID 24982845, 2014).
cancer (642 papers, 2002 to 2026). A tumor composed of atypical neoplastic, often pleomorphic cells that invade other tissues. "Galectin-1 and Galectin-3 modulate immune checkpoint pathways and cancer-associated fibroblast activation, whereas Galectin-9 interacts with TIM-3 to induce T-cell exhaustion." (PMID 42129932, 2026). "Galectin 3 is often elevated in cancer and is linked to tumor growth and spread, indicating a worse prognosis for patients with high levels." (PMID 39996744, 2025). "Galectin-3 expression is modulated in cancer cells, making it a potential diagnostic/prognostic marker for specific cancer types." (PMID 40284554, 2025). "The results identified four cancer types in which high LGALS3 expression levels were significantly associated with decreased overall survival." (PMID 41153387, 2025). "High levels of galectin-3 are associated with poor prognosis, as they play a role in cancer cell adhesion to the extracellular matrix and exhibit anti-apoptotic actions." (PMID 40426926, 2025). "While previous studies have implicated galectins, particularly Galectin-3, in cancer progression and resistance 27, our findings highlight the specific role of galectin-8 in Tarceva-resistant TNBC cells." (PMID 39895791, 2025). "Our study highlights the upregulation of galectin-3 as a significant effect of ALK4 loss in cancer cells, suggesting that the loss of ALK4 function alters the glycosylation and function of a number of cell surface and secreted proteins." (PMID 41408046, 2025). "galectin-3 expression inhibits cancer proliferation in neuroblastoma and is associated with better prognosis." (PMID 39408655, 2024). "The β-galactoside-binding lectin, Galectin-3, is involved in different immune processes and has been associated with poor outcome in various cancer diagnoses." (PMID 39759523, 2024). "The impedance biosensing platform is shown to selectively bind cancer-associated galectin-3 compared to control glycans and proteins." (PMID 39282644, 2024). "A glycofluoroform biosensor platform is coupled to an electrochemical readout to detect cancer-associated galectin-3." (PMID 39282644, 2024). "LGALS3 is a potential diagnostic and prognostic biomarker of several diseases, including cardiovascular, kidney disease, and cancer." (PMID 39911230, 2024). "In univariate analysis, higher galectin-3 levels were significantly associated with each cause of death—CV death, infection-related death, and malignancy-related death, respectively." (PMID 38195853, 2024). "Galectin-3 is upregulated in several cancers and is believed to be associated with glycolysis and mitochondrial metabolism in tumors." (PMID 38706841, 2024). "Galectin-3 is involved in regulating important cellular functions and has been linked to various human disorders, including cancer, fibrosis, and chronic inflammation." (PMID 38378809, 2024). "Studies have shown that galectin-3 can be a diagnostic or prognostic biomarker of many diseases, including cancer." (PMID 38144531, 2023). "For example, binding of galectin-3 to TF on cancer-associated transmembrane mucin protein MUC1 increases cancer cell heterotypic adhesion to vascular endothelium and promotes endothelial secretion of metastasis-promoting cytokines such as GM-CSF and IL-6." (PMID 37612278, 2023). "The function of Galectin-3 is also associated with RAS signaling in cancer since the CRD domain binds and stabilizes the active conformation of KRAS." (PMID 36873388, 2023). "Many of these cancer-promoting actions of galectin-3 have shown to be associated with galectin-3 interaction with galactoside-terminated cell surface glycoproteins." (PMID 37055381, 2023). "Galectin-3 is involved in many significant biological processes linked to cancer development and progression (20; reviewed by 21, 22; 19, 23)." (PMID 36936148, 2023). "Galectin-3 (Gal-3), a β-galactose-binding lectin, is a multifunctional protein associated with the development of many cancers." (PMID 37685842, 2023).
cancer (continued). "The endothelial adhesion of the cancer cells is also mediated by the recognition of galectin-3 by causing homotypic aggregation and promoting metastasis." (PMID 37444377, 2023). "We fitted a generalized linear model and noted a modest positive association (R2 = 0.01) between LGALS3 and cancer specific EMT signature scores." (PMID 38086828, 2023). "Galectin-3 inhibitors have been implicated as potential treatments for cancers, fibrotic diseases and other disorders." (PMID 36914828, 2023). "An aberrant expression of galectin-3 in distinct localization, specifically in cancers, has been associated with unique functions." (PMID 36713574, 2022). "Overexpression of galectin-3 is associated with enhancing metastasis and poor prognosis in several types of cancers, including colon, thyroid, gastric, liver, pancreatic ductal adenocarcinoma, bladder, and breast cancer." (PMID 37305017, 2022). "Alternatively, the downregulation of LGALS-3 has been detected to be associated with the progression of cancer cells." (PMID 37305017, 2022). "Galectin-3 (Gal-3) is a multifaceted protein involved in multiple pathophysiological pathways underlying chronic inflammation and cancer." (PMID 36612048, 2022). "After adjustment for age, sex, traditional CVRF, cancer and eGFR the risk for cardiovascular mortality was elevated by 53% per SD increase of galectin-3 and all-cause mortality was 40% higher in people with T2DM." (PMID 34561496, 2021). "This lectin family possesses a number of biological activities related to the development and progression of cancer, which is primarily associated with galectin-1 (Gal-1) and galectin-3 (Gal-3)." (PMID 34206141, 2021). "MUC1 with cancer-associated T antigen serves as a natural ligand of galectin-3 (Gal-3), a galactose-binding protein expressed inside cells, extracellularly (cell surface associated), and in the circulation." (PMID 34681197, 2021). "The expression of cancer-associated TF on MUC1 and its interaction with galectin-3 promote cancer cell adhesion to endothelium, encouraging thus directly cancer metastasis." (PMID 32280709, 2020). "On the other hand, β-galactose at the end of the abundant galactan side chains can bind to galectin-3 (a lectin associated with cancer), giving it higher anti-cancer potential than citrus or apple pectin." (PMID 33266001, 2020). "Accordingly, loss of Galectin-3 impairs mitochondrial morphology, with more fragmented and round mitochondria, and dynamics both in normal and cancer epithelial cells in basal conditions." (PMID 32398681, 2020). "Galectin-3 protects cancer cells from anoikis by causing a cell cycle arrest at the late G1 phase, which is an anoikis-insensitive point." (PMID 31683865, 2019). "Galectin-3 is one of the most studied galectins, and numerous reports have demonstrated that Gal-3 is directly associated with oncogenesis, angiogenesis, cancer progression, and metastasis." (PMID 31949431, 2019). "Galectin-3 is a type of lectin protein that is implicated in cancer, immune function and inflammation." (PMID 29670040, 2018). "One of the directions in antitumor research is the inhibition of galectin-3 (a lectin associated with cancer progression and metastasis)." (PMID 30961332, 2018). "Our results successfully identified the significant association of high galectin-3 expression with reduced DFS/RFS/PFS in overall cancer patients (pooled HR = 1.57, 95% CI 1.04–2.37, I2= 67.1%, p = 0.001)." (PMID 30410421, 2018). "In line with these, galectin-3 has been implicated in various systemic diseases, such as cancer, renal and cardiac fibrosis, and immunological disorders." (PMID 29414883, 2018). "Our results did indicate that high galectin-3 expression was significantly associated with unfavorable OS in overall cancer patients (pooled HR = 1.79, 95% CI 1.42–2.27, I2= 67.3%, p < 0.01)." (PMID 30410421, 2018). "The LGALS3 gene, encoding galectin-3, shows promoter methylation-dependent regulation in different cancers." (PMID 28481247, 2017).